PGD (phosphogluconate dehydrogenase)
Diseases named in the same sentence as PGD in open-access papers (continued):
Sharing a sentence is not in itself a finding about the gene and the disease.
tumor (34 papers, 2004 to 2026). "Expressions of immune checkpoints, most HLA members and tumor mutation burden (TMB) are higher in the high PGD expression group, which indicates beneficial efficacy of immunotherapy in this group." (PMID 36338768, 2022). "Here, we show for the first time the important role of PGD in CRC development elucidate the specific mechanism of the ATP13A2‐TFEB‐PGD signaling axis, complement the relationship between PGD and tumours, and partially explain the effect of ATP13A2 on CRC." (PMID 37243374, 2023). "The upstream lncRNA GSEC/miRNA-101-3p regulatory axis involving CISD1, ATP5MC3, and PGD was identified to be relevant in tumor progression." (PMID 35320929, 2021). "Our findings revealed that certain FRGs (CISD1, ATP5MC3, PGD, SLC7A11, ACSL3, and FANCD2) are significantly upregulated in LUAD and that their elevated expression is associated with both advanced tumor stage and unfavorable prognosis." (PMID 35320929, 2021). "6-Phosphogluconate dehydrogenase (6PGD) blockade in regulatory T cells (Tregs) prevents their suppressive function and induces potent anti-tumor responses." (PMID 34709178, 2021). "As expected, the mRNA level of PGD in tumour of ATP13A2−/− mice decreased." (PMID 37243374, 2023). "Although the role of PGD has been documented in various types of tumours, the relationship between PGD and CRC remains unclear." (PMID 37243374, 2023). "Analysis of gene expression, mutation, DNA methylation, and prognostic value in LUAD revealed CISD1, ATP5MC3, PGD, SLC7A11, ACSL3, and FANCD2 to be significantly upregulated in LUAD and elevated expression of these FRGs to be associated with advanced tumor stage and poor prognosis." (PMID 35320929, 2021). "Importantly, levels of ATP5G3, CISD1, and PGD expression were found to positively correlate with tumor stage." (PMID 35320929, 2021). "Besides, the alterations of AOX15, KRAS, and PGD mainly focused on domain lipoxygenase, Ras, and 6PGD, indicating that these domains played a crucial role in ferroptosis and tumor progression." (PMID 34434214, 2021). "Homozygous deletion of major tumor suppressor genes can result in the collateral deletion of chromosomal neighboring metabolic housekeeping genes, such as the pentose phosphate shunt enzyme 6-phosphogluconate dehydrogenase (PGD) at the 1p36 locus." (PMID 32587392, 2020). "Moreover, the expression of KRAS and PGD was positively related to tumor mutation burden, indicating that KRAS and PGD could serve as novel biomarkers for predicting immunotherapy response rate." (PMID 34434214, 2021). "Finally, CISD1, ATP5MC3, PGD, SLC7A11, ACSL3, and FANCD2 expression was confirmed to significantly correlate with tumor mutational burden (TMB), microsatellite instability (MSI), immune cell infiltration, cellular checkpoint dysfunction, and cancer sensitivity to drugs." (PMID 35320929, 2021). "IHC staining of mouse tumours revealed that ATP13A2−/− mice displayed significantly lower Ki67 and PGD protein expression than ATP13A2+/+ mice." (PMID 37243374, 2023). "In conclusion, GP5, CCT7, UQCRC1, PGD, GAPDH and LDHA have been found to play a role in tumor development, prognosis and even diagnosis in previous studies." (PMID 36404333, 2022). "An investigation of the correlation between FRG expression and tumor stage revealed only ATP5G3, CISD1, and PGD expression to positively correlate with the LUAD stage." (PMID 35320929, 2021). "PGD is an enzyme that mediates the third step of the pentose phosphate pathway (PPP) and is overexpressed in multiple tumor cells, promoting the proliferation, survival, and metastasis of tumor cells through reprogrammed tumor bioenergetics." (PMID 35111195, 2021). "K294 acetylation in 6-phosphogluconate dehydrogenase (6-PGD) was regulated by ACAT2, which was related to NADPH production and tumor growth." (PMID 34664012, 2021). "Lower expression in cell lines was seen in KIF1B and equal levels of cell lines and stage 2 primary tumours in UBE4B, PGD and PEX14." (PMID 15740626, 2005).
tumor (continued). "Here the authors show that 6-phosphogluconate dehydrogenase (6PGD) is important for MSDC function and that blockade of 6PGD impaired MDSC function and suppresses tumour growth leading to metabolic and functional changes in the MDSC and a more pro-inflammatory phenotype." (PMID 41535266, 2026). "Additionally, GSEA revealed that increased PGD gene expression levels were correlated with MDSC gene signatures in the dataset, suggesting high infiltration of MDSC in high PGD-expressing tumor." (PMID 41535266, 2026). "As ferroptosis plays crucial roles in both immunity and pulmonary carcinogenesis, the correlation between CISD1, FANCD2, PGD, ASCL3, ATP5MC3, and SLC7A11 expression and tumor immune infiltration in LUAD was evaluated utilizing data obtained from the TIMER database." (PMID 35320929, 2021). "Moreover, we find that PPP activity was strongly higher in resistant cells and tumor tissues and that forced PPP activity was resulted by PGD overexpression." (PMID 32719331, 2020). "Collectively, our results suggest that ATP13A2 affects PGD expression to regulate the PPP, which not only promotes the proliferation of CRC cells but also enhances their ability to resist oxidative stress, supporting CRC cell survival in the real tumour environment." (PMID 37243374, 2023). "The genes UBE4B, KIF1B, PGD, APITD1, DFFA and PEX14 are down-regulated in high stage NB tumours, a feature that can not be explained by CpG island methylation." (PMID 15740626, 2005). "The analyzed fragments of the genes UBE4B, KIF1B, PGD, DFFA and PEX14 were not methylated in the panel of NB primary tumours and cell lines." (PMID 15740626, 2005). "Hence, the six genes UBE4B, KIF1B, PGD, APITD1, DFFA and PEX14 are down-regulated in high stage NB tumours, a feature that can not be explained by methylation, rather by a mechanism still remaining to be discovered." (PMID 15740626, 2005).
infection (2 papers, 2020 to 2021). The state of being infected such as from the introduction of a foreign agent such as serum, vaccine, antigenic substance or organism. "Furthermore, the kinetics of mRNA levels indicated higher expression of G6PD2, G6PDX and PGD in myoblasts particularly at 4 hours p.i. and a decline until 24 hours of infection." (PMID 34881198, 2021). "To determine the impact of PGD on GIST cells, we elevated PGD expression in GIST-T1S and GIST-882S cells, and repressed its expression in GIST-T1R and GIST-882R cells by lentivirus infection and verified the altered expression of PGD in these GIST cell lines by qRT-PCR and western blotting." (PMID 32719331, 2020). "To better understand the influence of HIF-1α on PGD expression in GIST cells, we downregulated HIF-1α expression in GIST-T1R and GIST-882R cells by lentivirus infection and verified the altered expression of HIF-1α in these GIST cell lines by western blotting." (PMID 32719331, 2020).
bacterial infection (1 paper, 2022). "In summary, pathogenic bacterial infection upregulated PKM, LDHB, LDHA, ALDOA, PGD, GPI, and ALDOC, increased ATP production, which promotes leukocyte recruitment and NALP3-inflammasome activation, increases NADPH production, and promotes ROIs modulating inflammation and injury." (PMID 36335251, 2022).
PGD also shares sentences with these, for which no sentence is quoted: colorectal cancer (4 papers); ovarian carcinoma (2); Autoimmunity (1); bipolar disorder (1); Bladder Urothelial carcinoma (1); Breast invasive carcinoma (1); bronchiectasis (1); colorectal tumor (1); frontotemporal lobar degeneration (1); glioblastoma (1); head and neck cancer (1); hepatitis B virus infection (1); hepatocellular carcinoma (1); hyperprolactinemia (1); large cell lung cancer (1); leukemia (1); lung squamous cell carcinoma (1); lymph node metastasis (1); melanoma (1); Parkinson disease (1); prostate carcinoma (1).